DDX5 (DEAD-box helicase 5)
Diseases named in the same sentence as DDX5 in open-access papers (continued):
Sharing a sentence is not in itself a finding about the gene and the disease.
breast carcinoma (continued). "Next, we examined how the expression levels of DDX5, DDX17, and DGCR8 genes correlate with breast cancer patients’ survival." (PMID 34117091, 2021). "Reportedly, the methods developed in this study were successful in determining the spatial variation in the expression of 102 genes, including several breast cancer biomarkers such as GNAS, FASN, and DDX5." (PMID 34441338, 2021). "The analyses revealed that the key components of microprocessor complex such as DGCR8, DDX5, and DDX17 are down-regulated in breast cancer as compared with the healthy samples." (PMID 34117091, 2021). "This promotes DDX5/Drosha/DGCR8 complex formation and miR-10b processing in breast cancer." (PMID 37762595, 2023). "Accordingly, DDX5 is overexpressed in basal-like tumors, and DDX5 levels are predictive of worse outcomes in ER- but not ER+ breast cancers." (PMID 37176013, 2023). "DDX5 has been found to regulate the biogenesis of a subset of miRNAs, targeting different downstream mRNAs (e.g., PDCD4 via miR-21, cofilin and profilin via miR-182) and thus promoting the progression of breast cancer." (PMID 35954483, 2022). "For example, in breast cancer, both DDX3X and DDX5 act as oncogenes." (PMID 35954483, 2022). "However, some studies indicate that DDX5, DDX21, and DDX3X exert tumor suppressor function in different cancers, such as hepatocellular carcinoma (HCC), breast cancer (BC) and colorectal cancer (CRC)." (PMID 35723050, 2022). "Although WBP2 did not regulate the expression level of the microprocessor complex components, that is, DGCR8, Drosha, DDX5, and DDX17, it suppressed the activity of pri-miRNA–processing machinery via physical interactions with these components in breast cancer." (PMID 34117091, 2021). "Importantly, DDX5 interaction with the BRCA2 mutant T207A, found in breast cancer cells from patients, is reduced compared to wild-type BRCA2, and R-loops levels are increased in cells that overexpress this variant." (PMID 34359660, 2021). "Estrogen-regulated genes were not enriched in our U2OS data, as these are likely occurring in a tissue-specific manner in breast cancer cell lines and how DDX5 gets recruited at these sites is not known." (PMID 32747416, 2020). "In contrast, it was reported that DDX5 is involved in TGF-β (transforming growth factor-β)- and BMP (bone morphogenic protein)-specific SMAD signaling-induced oncogenic miR-21 maturation by forming a protein complex with Drosha-DGCR8 in breast cancer cells 166,167." (PMID 38689093, 2024). "DDX5 enables LMTK3 to facilitate the processing of pri-miRNAs (pri-miR-34a, pri-miR-182, and pri-miR-196-a2) for maturation, and upregulated miR-34a and miR-182 can target and inhibit LMTK3 expression, consequently suppressing the oncogenic effects of LMTK3 in breast cancer." (PMID 38689093, 2024). "In addition, β-catenin and transcription factor 4 (TCF4) can bind to the promoter of the DDX5 gene to stimulate the expression of DDX5, which in turn promotes the transcription of the β-catenin-dependent TCF4 gene, forming a positive feedback loop to promote breast cancer progression." (PMID 35992805, 2022). "Combined DDX5/DDX17/DGCR8 expression profiles as a signature showed a stronger effect, HR = 0.47 (95% CI: 0.4-0.55, logrank P-value = 1 × 1016), meaning that lower expression of this set of signature genes correlated with ∼2 times increase in the survival of breast cancer patients." (PMID 34117091, 2021). "In the case of breast cancer, the DEAD box helicase, DDX5, was found to be amplified and often co-amplified along with ERBB2, and breast cancer cell lines with amplification of the DDX5 locus were considerably more sensitive to its knockdown than breast cancer cell lines lacking this amplification." (PMID 23116066, 2012).
colorectal cancer (22 papers, 2015 to 2026). A primary or metastatic malignant neoplasm that affects the colon or rectum. "For example, we previously reported that nuclear-enriched abundant transcript 1 (NEAT1) facilitates colorectal cancer progression by stabilizing the DEAD-box helicase 5 (DDX5) and activating Wnt/β-catenin signaling pathway." (PMID 41484982, 2026). "Among them, FL118 has shown potent antitumor effects by reducing DDX5 expression in models of pancreatic and colorectal cancer, as well as chronic myeloid leukemia." (PMID 40950397, 2025). "Wang's study demonstrated that SNHG14 enables the proliferation and invasion of colorectal cancer cells by mediating the miR‐519b‐3p/DDX5 axis." (PMID 40521987, 2025). "NEAT1 indirectly activates the Wnt/β-catenin signaling pathway through DDX5 to promotes colorectal cancer progression." (PMID 35992805, 2022). "LncRNA NEAT1 activates Wnt/β-catenin signaling and promotes colorectal cancer progression via interacting with DDX5." (PMID 35477447, 2022). "In accordance with our study, Lnc NEAT1 activates Wnt/β-catenin signaling and contributes to colorectal cancer progression via DDX5." (PMID 35850692, 2022). "We examined the expression of OGT, DDX5, and O‐GlcNAcylation in four colorectal cancer cell lines (HT29, HCT116, SW480, SW620) and the normal human intestinal epithelial cell line NCM460." (PMID 30484950, 2019). "Also, we observed a positive correlation between the expression levels of circASCC3 and DDX5 in ten colorectal cancer samples." (PMID 40067902, 2025). "Also, NEAT1 activates Wnt signaling by interacting with DDX5 to promote colorectal cancer progression." (PMID 36787190, 2023). "LncRNA NEAT1 also could promote the progression of colorectal cancer by activating Wnt/β-catenin signaling through interaction with DDX5." (PMID 35300348, 2022). "Finally, we found that SNHG14 promotes cell proliferation and invasion in colorectal cancer through modulating miR-519b-3p/DDX5 axis." (PMID 34234865, 2021). "Then, we further clarify whether there is also a correlation between DDX5 and O‐GlcNAcylation in colorectal cancer cell lines." (PMID 30484950, 2019). "Our results indicate that OGT can directly interact with DDX5 in colorectal cancer cell lines." (PMID 30484950, 2019). "Here, we found both DDX5 and O‐GlcNAcylation are up‐regulated in colorectal cancer." (PMID 30484950, 2019). "In colorectal cancer, SNHG14 modulates the miR-519b-3p/DDX5 axis to promote cell proliferation and invasion." (PMID 40561678, 2025). "In colorectal cancer (CRC), for example, DDX5 directly interacts with β-catenin to act as a transcriptional co-activator, upregulating FOXM1 and promoting tumor progression." (PMID 40950397, 2025). "OGT-mediated O-GlcNAcylation stabilizes DDX5, activates the AKT/mTOR signaling pathway, and then accelerates the progression of colorectal cancer." (PMID 35992805, 2022). "DDX5 is a member of the DEAD-Box protein family, and it has been reported to be involved not only in various types of cancer, such as colorectal cancer, lung cancer, and hepatic cancer but also in cases of viral infection." (PMID 36246972, 2022). "In colorectal cancer, this signaling is activated by the interaction of NEAT1 (nuclear enriched abundant transcript 1) with DDX5 to promote cancer and metastasis." (PMID 35954483, 2022). "In colorectal cancer cells, NEAT1 directly binds to the DDX5 protein, maintains its stability, and activates the Wnt signaling pathway." (PMID 32922184, 2020). "We knocked down DDX5 in SW480 and found that it can significantly inhibit colorectal cancer proliferation." (PMID 30484950, 2019). "This study not only reveals the novel functional of O‐GlcNAcylation in regulating DDX5, but also reveals the carcinogenic effect of the OGT‐DDX5 axis in colorectal cancer." (PMID 30484950, 2019).
colorectal cancer (continued). "In this study, we demonstrated that O‐GlcNAcylation of DDX5 is involved in colorectal cancer progression by activation of AKT/mTOR signalling pathway, which opens up a new sight for the treatment of colorectal cancer." (PMID 30484950, 2019). "Taken together, these results indicated that OGT‐mediated O‐GlcNAcylation stabilizes DDX5, promoting activation of the AKT/mTOR signalling pathway, thus accelerating colorectal cancer progression." (PMID 30484950, 2019). "The RNA helicase p68 (DDX5), a key player in RNA metabolism, belongs to the DEAD box family and is involved in the development of colorectal cancer." (PMID 30484950, 2019). "In colorectal cancer (CRC), the oncogenic function of DDX5 has been observed in various studies." (PMID 35954483, 2022). "Since DDX5 and DDX17 are known mediators of Wnt signaling in colorectal cancer and DDX3 and DDX5 have been found to interact, we evaluated whether RK-33 treatment also influences DDX5 and DDX17 protein levels." (PMID 26311743, 2015).
viral infection (22 papers, 2011 to 2025). "Notably, DDX5 has been associated with multiple viral infections." (PMID 37007947, 2023). "Then, based on the interaction of DDX5 and NP, we speculated that influenza virus infection may cause changes in the expression and nucleocytoplasmic distribution of DDX5, such as have been reported in other viral infections." (PMID 35583334, 2022). "DDX5 is also involved in cellular differentiation, embryonic development, metabolism, as well as viral infection." (PMID 38182816, 2024). "An increasing number of studies have revealed the functionality of DDX5 in cell cycle regulation, tumorigenesis, and viral infection." (PMID 39287046, 2024). "Human DDX5 and its yeast ortholog Dbp2 are ATP-dependent RNA helicases that play a key role in normal cell processes, cancer development, and viral infection." (PMID 36894019, 2023). "Together, these studies indicate that DDX5 promotes virus infection and replication and suppresses IIRs." (PMID 37596619, 2023). "In this regard, DDX5 would be a good target for the restriction of virus infection and replication as well as activating IIRs." (PMID 37596619, 2023). "In this section, we review relevant new publications on the role of DDX5 in viral infection and innate immune responses (IIRs)." (PMID 37596619, 2023). "Taken together, these data indicated that DDX5 participated in the formation of the m6A writer complex after viral infection." (PMID 33909701, 2021). "This suggested that DDX5 exert crucial responsibility to RNA degradation of antiviral transcripts during viral infection." (PMID 33909701, 2021). "For example, included as a protein unique to CRL4HBV is DEAD box protein 5 (DDX5), an RNA helicase that has an emerging regulatory role in viral infections, including HBV." (PMID 32235678, 2020). "The roles of DDX5 in cell cycle regulation, tumorigenesis, apoptosis, cancer development, adipogenesis, Wnt-β-catenin signaling, and viral infection have been established." (PMID 29642538, 2018). "As summarized in this review, the multifaceted protein DDX5 has been shown to be involved in RNA metabolism and viral infection, especially for RNA viruses." (PMID 29642538, 2018). "Here, we provide a rapid and critical overview of the structure and functions of DDX5 with a particular emphasis on its role during virus infection." (PMID 29642538, 2018). "In view of the importance of DDX5 in regulating virus infection, we here provide a brief and critical overview of the known functions of DDX5, with a particular emphasis on its role during the virus life cycle." (PMID 29642538, 2018). "DEAD-box protein (DDX) 5 plays important roles in multipleaspectsof cellular processes that require modulation of the RNA structure.Alongside the canonical role in RNA metabolism, numerous studies havedemonstrated that DDX5 influences viral infections by directly interactingwith viral proteins." (PMID 40821550, 2025). "Interestingly, JINR1 also binds and sequesters miR-216b-5p and miR-1-3p, resulting in upregulation of their targets GRP78 and DDX5, respectively, which promote viral infection." (PMID 40272157, 2025). "In contrast, we demonstrated that the single depletion of DDX17 reduces SINV infection in HCT116 cells and its combined depletion with DDX5 in the KO background further decreases viral levels, suggesting a synergism between the two proteins in promoting viral infection." (PMID 38553727, 2024). "We proceeded to investigate whether DDX17 acts in synergy or competition with DDX5 by analysing the impact of DDX17 knockdown in DDX5 KO HCT116 cells where viral infection is already weakened." (PMID 38553727, 2024). "Specifically, in this review we will discuss the diverse roles of DDX5 in DNA repair, immune suppression, cancer metabolic control, virus infection promotion, and negatively impacting microbiota, which in aggregate, support the notion that DDX5 is a master oncogenic regulator." (PMID 37596619, 2023).
viral infection (continued). "While DExH/D-box helicases could either promote or inhibit the viral infection, evidence indicated that DDX5 can act as a helper or inhibitor for viral infection and play a role in innate immune suppression." (PMID 37596619, 2023). "Additionally, the significance of DDX5 in promoting virus infection and replication has been identified." (PMID 37596619, 2023). "Thus, targeting DDX5 would counteract virus infection and replication and enhance IIRs against human disease including virus infection and cancer." (PMID 37596619, 2023). "To further investigate whether human DDX5 negatively regulates viral infection-induced IFN responses, we then detected the IFN-I signaling in A549 cells infected with WSN/1933." (PMID 35583334, 2022). "Consequently, DDX5 played vital roles in cellular RNA metabolisms to negatively regulate innate immune response to viral infection." (PMID 33909701, 2021). "Similarly, a DDX5 inhibitor is undergoing clinical trials, and due to DDX5's predominantly proviral role, this inhibitor may also prove valuable in treating viral infections." (PMID 39620586, 2025). "Therefore, pharmacological inhibition or degradation of DDX5 may provide effective strategies to enhance IIRs against virus infection, replication, and other human diseases including cancer." (PMID 37596619, 2023). "This demonstrates a conserved function of gammaherpesviral protein kinases to interact with DDX5 and DDX17 and utilize these host proteins for viral infection." (PMID 40257982, 2025). "DDX5 and DDX17 promote virus infection by enhancing viral gene expression via recruitment of host protein Brg1, a chromatin remodeler." (PMID 40257982, 2025). "To establish the involvement of DDX5 during JEV/WNV infection in SH-SY5Y cells, we first did a time course analysis of its mRNA and protein expression during viral infection." (PMID 40272157, 2025). "Previous studies have demonstrated an interaction between DDX5 and METTL3, as well as an interaction between METTL3 and METTL14 to form a m6A writer complex upon virus infection." (PMID 38182816, 2024). "The N protein of SARS-CoV-2 has been found to interact with several RNA helicases, including DDX1, DDX3, DDX5, DDX6, DDX21, and DDX10; among them, DDX1, DDX5, and DDX6 are essential for virus replication, while DDX21 and DDX10 restrict the viral infection." (PMID 38328580, 2023). "Meanwhile, DDX5 promoted the m6A modification and nuclear export of transcripts DHX58, p65, and IKKγ by binding conserved UGCUGCAG element in innate response after viral infection." (PMID 33909701, 2021). "Moreover, we show that JINR1 sponges miR-216b-5p and miR-1-3p during viral infection to enhance the expression of their target genes GRP78 and DDX5, respectively, thereby promoting viral infection." (PMID 40272157, 2025). "A growing body of evidence suggests that DDX5 and DDX17 play crucial roles during viral infection." (PMID 38553727, 2024). "In conclusion, this study uncovers DDX5 as a novel positive host factor for the prototype alphavirus SINV and significantly advances our understanding of the role played by RNA helicases in viral infections." (PMID 38553727, 2024). "In this review, we discuss the multifaceted functions of DDX5 in DNA repair in cancer, immune suppression, oncogenic metabolic rewiring, virus infection promotion, and negative impact on the human microbiome (microbiota)." (PMID 37596619, 2023). "Some act as viral sensors (DDX3, DDX41, DHX9, DDX1/DDX21/DHX36 complex), and others have roles in innate immune activation (DDX60, DDX60L, DDX23), and still others (DDX39A, DDX46, DDX5 and DDX24) act as negative regulators and impede interferon (IFN) production upon viral infection." (PMID 37596619, 2023). "Coincidentally, the interaction of DDX5 and METTL3 has also been found in macrophage lipid uptake, which indicated that METTL3 is the pivotal target of DDX5 in cellular development and viral infection." (PMID 33909701, 2021).
viral infection (continued). "In our study, we found that the interaction of DDX5 and METTL3 was enhanced by viral infection." (PMID 33909701, 2021). "Given that various members of the DDX family (including, but not limited to, DDX3, DDX5, and DDX56) exhibit distinct regulatory effects on different viral infections, further studies are warranted to determine whether DDX43 exerts a proviral or antiviral effect on other viruses." (PMID 41157636, 2025). "For instance, DDX5 activity as a regulator of N6-methyladenosine levels on the DHX58 and NF-κB mRNAs could negatively impact antiviral innate immunity and therefore enhance viral infection." (PMID 38553727, 2024).